DNMT3B (DNA methyltransferase 3 beta)
Diseases named in the same sentence as DNMT3B in open-access papers (continued):
Sharing a sentence is not in itself a finding about the gene and the disease.
cancer (continued). "Additionally, only DNMT3B was significantly downregulated in MSCs vs. cancer cell lines." (PMID 39621192, 2025). "In addition, the knockdown of DNMT3b or decitabine sensitizes cancer cells to enzalutamide." (PMID 38988323, 2024). "Notably, DNMT3B was differentially expressed in all cancers." (PMID 39186807, 2024). "Additionally, HDAC6 and DNMT3B are emerging as important therapeutic targets for cancer." (PMID 39411320, 2024). "In addition, we analyzed the correlation between PGAM1 and methylation-related genes, and the results showed that PGAM1 had significant correlations with methyltransferases such as DNMT1, DNMT3A and DNMT3B as well as methylation modifications such as m1A, m5C and m6A across various cancers." (PMID 38434965, 2024). "Next, we examined whether DNMT3B expression is increased in cancer patients." (PMID 36460706, 2022). "In addition, DNA methylation may play an important role in tumor progression, and PBK/TOPK expression was positively correlated with methyltransferase expression, including DNMT1, DNMT3A, and DNMT3B, in most cancers except CHOL." (PMID 34603451, 2021). "It would also be critical to elucidate whether DNMT3B plays similar roles in other cancers, especially other aggressive cancers characterized by activation of oncogenes (e.g., pancreatic cancer), and whether PTS effects on DNMT3B binding and histone mark occupancy occur in different cancer types." (PMID 34439480, 2021). "Similarly, a strong interaction between DNMT3B with H3K36me3 is observed both in mouse and human embryonic stem cells, which is important for regulating cell type-specific genes expression as well as cancer establishment and progression." (PMID 33649938, 2021). "Although there is not much evidence for DNMT3B mutations in cancer, increased expression of DNMT3B is found in some tumors, which suggests that abnormal expression of DNMT3B may silence TSGs." (PMID 32751889, 2020). "The present study revealed an association between a functional polymorphism of DNMT3B and MTHFR methylation levels that could be of relevance in those disorders, such as inborn defects, metabolic disorders and cancer, that have been linked to impaired DNA methylation." (PMID 31370354, 2019). "A particular emphasis will be given to traditional and novel functions of DNMT3B that is the major de novo DNA methyltransferase active during implantation and is impaired in human diseases with chromosomal and genomic instabilities, including inherited disease and cancer." (PMID 30406101, 2018). "Indeed, analysis of Cancer Cell Line Encyclopedia confirmed that Ets1 expression was negatively correlated with Dnmt3a (Spearman r = −0.4139, **p = 0.0011) and Dnmt3b (Spearman r = −0.5878, ***p < 0.0001) but positively with Apobec3c (Spearman r = 0.6239, ***p < 0.0001)." (PMID 30467308, 2018). "However, the role of Dnmt3a and Dnmt3b in many types of cancer remains undefined." (PMID 28425913, 2017). "Since aberrant DNA methyltransferases (Dnmts) activity has been reported in numerous cancers, we examined the expression of the 3 major Dnmts: Dnmt1, Dnmt3a and Dnmt3b which are known to be involved in DNA methylation maintenance (Dnmt1) or de novo methylation (Dnmt3a and Dnmt3b)." (PMID 29073177, 2017). "Mirza and colleagues reported decreases in the transcript levels of DNMT1, DNMT3A and DNMT3B with the incorporation of WA, and use their findings to suggest that WA may have beneficial therapeutic effects against cancer through its ability to reverse changes in the epigenome." (PMID 28534825, 2017). "Thus, DNMT3b downregulation may represent an advantage for cancer development, driving the expansion of the stem cell compartment." (PMID 26556862, 2016). "Interestingly, many aberrant transcripts of DNMT3B are highly expressed in cancer cells." (PMID 25607950, 2015). "Additionally, we examined whether DNMT3B dysfunction induced radiosensitization in other cancer cell lines exhibiting high DNMT3B expression." (PMID 26667181, 2015).
cancer (continued). "However, unlike other genes that are overexpressed in cancer as a result of genetic mutations and/or gene amplifications, the mechanisms accounting for overexpression of DNMT3b does not involve these changes." (PMID 24297604, 2014). "However, unlike other genes that are overexpressed in cancer, the mechanisms accounting for increased DNMT3b levels infrequently involve gene mutations and/or gene amplification." (PMID 22664488, 2012). "Finally, the previously noted similarities in pluripotent and cancer stem cell gene expression patterns suggest that DNMT3B exon 10 may be a specific biomarker of the stem cell component of some tumors." (PMID 21698279, 2011). "In the process of cancer development, various DNMTs (DNMT1, DNMT3A, and DNMT3B) and HDACs (HDAC 1, 2, 3, and 6) are reported to be overexpressed in different cancers." (PMID 41562705, 2026). "Based on the UMAP plot retrieved from the Ovary Cancer sc Database, the plot suggests an inverse spatial expression pattern between CDH1 and DNMT3B in several regions." (PMID 41596471, 2026). "This study proposed a putative axis of piR-823/PIWIL1/DNMT3B/CDH1 that appears to be involved in EMT and cancer stemness in OC, providing a basis for future mechanistic studies." (PMID 41596471, 2026). "Upon treatment of the different cancer cell lines (HaCaT, HepG2, and A549 cells) with TRZ in our study, DNMT1, DNMT3a, and DNMT3b were significantly upregulated at concentrations of 20, 40, and 80 μM for a duration of 24 h." (PMID 40077783, 2025). "The primary function of DNMT1 is maintaining CpG methylation status during cell division (maintaining the cancer stem cell status), while DNMT3A and DNMT3B are predominantly involved in de novo methylation." (PMID 40507223, 2025). "In line with this study, kaempferol was found to reduce DNMT1, DNMT3B and HDAC activity in different cancers." (PMID 40159638, 2025). "Of the 3 genes included in the panel of epigenetic regulators, DNMT3B (DNA methyltransferase 3 beta) and JARID2 (Jumonji and AT-rich interaction domain containing 2) were overexpressed in iPSCs compared to MSCs and cancer cell lines." (PMID 39621192, 2025). "For DNA methylation regulatory factors, the specific functions and molecular mechanisms of DNMT1, DNMT3A, DNMT3B, and TET family proteins have been extensively studied in various malignant tumors." (PMID 38308276, 2024). "It has been demonstrated that in various types of cancers, DNMT1 and DNMT3B act as the leading catalyzers of TSGs methylation silencing." (PMID 38504782, 2024). "DNMT1, DNMT3b, HDAC1, and HDAC3 have been reported to be highly expressed in choriocarcinoma cancer stem-like cells." (PMID 38988323, 2024). "With the assistance of RALY, PTBP1 can bind to the pre‐mRNA of DNMT3B and drive an oncogenic splicing switch in DNMT3B to produce DNMT3B‐L, which in turn induces promoter methylation of DUSP2, thereby increasing resistance of cancer cells to irradiation." (PMID 39287090, 2024). "It is possible that DNMT3B regulates the expression of PFKFB4 by methylating its promoter region, thereby modulating glycolytic activity in cancer cells." (PMID 39595571, 2024). "Consistent with the role of miR-29s in cancer, their targets DNMT3A and DNMT3B have been described as overexpressed in various neoplasms and associated with poor prognosis in numerous tumors, including BC." (PMID 37373065, 2023). "The relationship between the expression of four methyltransferase genes (DNMT1, (DNMT2, DNMT3A, DNMT3B) and SNAI2 in pan-cancer was investigated further." (PMID 37251370, 2023). "Aberrant methylation often results in cancer development through the many-fold expression of DNA methyltransferases (DNMT1, DNMT3a, and DNMT3b) that is comparatively significantly higher than their normal expression in healthy cells." (PMID 36765652, 2023).
cancer (continued). "Overexpression of LinC00472 can recruit DNMT1, DNMT3A and DNMT3B to mediate the methylation of oncogenic factor MCM6, which leads to the down-regulation of its expression level, and then inhibits cancer progression by inactivating MEK/ERK signaling pathway." (PMID 37901333, 2023). "In type I cancer cells, DNMT1 and DNMT3b were preferably upregulated, but downregulated in type II cancer cells." (PMID 37368179, 2023). "However, the mechanistic basis for the fundamental roles of DNMT3A and DNMT3B in tumorigeneses and cancer progression remains largely unknown, and it therefore becomes important to understand the underlying mechanism determining their occupancies on chromosomes and their distinct functions." (PMID 37072414, 2023). "DNMT1 and DNMT3b cooperate to silence genes in human cancer cells, and deletion of DNMT1 and DNMT3b eliminates methyltransferase activity and reduces genomic DNA methylation (global DNA hypomethylation) by greater than 95%." (PMID 37772039, 2023). "At the same time, in an in vitro study of curcumin in several human cancer cell lines, curcumin induced some global DNA hypomethylation and altered the expression of three DNMTs: DNMT1, DNMT3A, and DNMT3B." (PMID 36499286, 2022). "DNMT3B (as well as DNMT1 and DNMT3A) is frequently overexpressed in different cancer types, including nasopharyngeal carcinoma (NC)." (PMID 34681626, 2021). "To further support our result that down-regulation of miR-145 is mediated via DNA methylation, we examined the expression of DNMT3B in OSCC tissues and various cancer cell lines by qRT-PCR." (PMID 34946098, 2021). "All three genes from this locus that are listed as cancer-related at OncoKB knowledgebase (ASXL1, DNMT3B, BCL2L1) are amplified in the 12 cell lines." (PMID 34577783, 2021). "A positive feedback loop between DNMT3B and TERT has been suggested through a positive correlation in their expression in a wide range of cancer types within the Cancer Genome Atlas (TCGA) dataset." (PMID 33802026, 2021). "Palakurthy has shown that DNMT3B is the target of HOXB3 protein and is involved in the epigenetic regulation of tumor suppressor gene RASSF1A in lung adenocarcinoma and other cancers." (PMID 34722321, 2021). "DNMT3B- and OCT1-mediated mechanisms, through which stilbenoids modify DNA methylation and impact the expression of genes involved in cancer, are an emerging research area." (PMID 34439480, 2021). "DNMT3B is overexpressed in GC and it cooperates with DNMT1 to silence tumor suppressor genes in cancer." (PMID 31534549, 2019). "To evaluate their relationship in cancer, we examined the Cancer Genome Atlas (TCGA) dataset via cBioPortal and observed a consistent positive correlation between TERT and DNMT3B expression in the majority of cancer types." (PMID 31284662, 2019). "Exposing cancer cells to gamma irradiation has been reported to decrease the protein levels of DNMT1 and DNMT3b." (PMID 30158986, 2018). "To test potential DNMT involvement in VEGFA‐driven miR‐128‐2 repression, and since DNA methyltransferases genes, DNMT3A, DNMT3B, DNMT1, are often coregulated and elevated in cancer stem‐like cells, we assayed all three methyltransferases." (PMID 28179359, 2017). "mRNA expression of DNMT1, DNMT3A, DNMT3B, and six different isoforms of DNMT3B were examined by real-time PCR, with only DNMT3B4 exhibiting significantly different expression levels between cancer tissues and adjacent normal tissues." (PMID 28160561, 2017). "Human cancer cells with DNMT1 knockout were found to retain their inherited methylation pattern, suggesting maintenance activity by the expressed DNMT3a and DNMT3b." (PMID 28052028, 2017). "To further evaluate the impact of promoter methylation on gene expression, we utilized two cancer cell lines, namely HCT116 wild type and HCT116DNMT1−/− DNMT3B−/− double knockout (DKO) cells." (PMID 26300991, 2015).
cancer (continued). "Existing data has implied that Lsh interacts predominantly with the de novo methyltransferases Dnmt3a and Dnmt3b in MEFs, while this interaction occurs by means of HDAC1 and HDAC2 in transformed cancer cells (HCT116)." (PMID 26491684, 2015). "A regulator of de novo DNMTs, DNMT3a and DNMT3b, DNMT3L promoter was found to have lost DNA methylation to varying levels in 14 out of 15 cancer cervix samples that were analyzed." (PMID 24822169, 2014). "Nonetheless, many genes that have been described as targets of Dnmt3b in the mouse, including MAEL, SYCE1, and SYCP1, are aberrantly expressed in human cancers and are listed as cancer testes genes." (PMID 25198254, 2014). "At that time, several mRNA targets of miR-148a such as DNA methyltransferase 3 beta (DNMT3B), DNA methyltransferase 1 (DNMT1), BCL2 were described in various cancers using transient transfection and Western blot analysis." (PMID 23383211, 2013). "DNMT1 and DNMT3B colocalize in the nucleus, and it has been shown that in cancer cells DNMT1 and DNMT3B work cooperatively to maintain DNA methylation." (PMID 22382075, 2012). "Together, these results further indicate that a combined inhibition of DNMT3B and DNMT1 is particularly effective for the demethylation of genes aberrantly hypermethylated in cancer." (PMID 22563479, 2012). "In various cancer cell lines, the DNMT isoforms DNMT1 and DNMT3B are up-regulated, and as a result, the promoter region of p16INK4A is hypermethylated." (PMID 21572997, 2011). "Recently, MYC protein recruited the PRC2/EZH2/DNMT3B complex to bind to the RASSF1A promoter, which led to RASSF1A gene silencing by promoter CpGs hypermethylation and condensed chromatin in cancer cell." (PMID 20877461, 2010). "Aberrant CpG-island methylation in cancer is regulated by DNMT1, DNMT3A and DNMT3B which catalyze the transfer of a methyl moiety from the methyl donor S-adenosyl-L-methionine to the carbon-5 of a cytosine base." (PMID 21629434, 2010). "Nonetheless, the presently unknown cause of the hypomethylation of both satellite 2 and satellite α in the ICF cases where DNMT3B mutations have not been found might be related to the cause of hypomethylation of classical satellite 2 and centromeric satellite α in cancer." (PMID 16722602, 2006). "Epigenetic regulation and metabolic pathways are known to be interconnected, and there is evidence to suggest that DNMT3B and PFKFB4 may interact in a manner that contributes to the development and progression of cancer." (PMID 39595571, 2024). "Therefore, it is possible that DNMT3B and PFKFB4 interact through the PI3K/AKT pathway to regulate glycolytic activity and promote cancer progression." (PMID 39595571, 2024). "For the remaining 17 genes, DNMT3B, RARB, SMAD5, SMARCA5, SMARCC1 and TGFBRAP1 were predicted only by our method, but various evidence suggests that they have a driving role in cancer development." (PMID 39186807, 2024). "It will likely prove important in determining how DNA methylation changes occur in cancer, where the role of DNMT3A and DNMT3B remain unclear despite reported mis-regulation, altered splicing and mutations." (PMID 39446312, 2024). "By analyzing the expression patterns of these DNA methylation writers and erasers, we observed that the most notable alterations in cancers were elevated levels of DNMT1, DNMT3A, and DNMT3B, which is consistent with the previous result of global DNA hypermethylation in a broad array of cancers." (PMID 38666956, 2024). "Lastly, we have carried out our experiments in human cancer cells, but it will be worthwhile in the future to clarify whether UHRF1 also promotes DNMT3A/DNMT3B activity in other systems, such as mouse embryonic stem cells." (PMID 38580649, 2024). "Additionally, it has been shown that H19 functions as a ceRNA to prevent miRNAs from degrading the essential transcriptional regulator DNA (cytosine-5)-methyltransferase 3B (DNMT3B), which is connected to the development of EMT in cancer." (PMID 36902032, 2023).
cancer (continued). "In cell-based and in vivo cancer models, only DNMT3B enzymatic activity, and not DNMT1 or DNMT3A, affects Ccnd2 expression." (PMID 36739439, 2023). "Additionally, we explored the correlation between IL18RAP and five methyltransferases (DNMT3L, DNMT3B, DNMT3A, TRDMT1, and DNMT1) across cancers." (PMID 37698530, 2023). "Interestingly, in the context of its epigenetic role, studies have confirmed that CHD4 can interact with the methylation enzymes DNMT1, DNMT3B, EZH2 and G9a in cancer progression." (PMID 36681835, 2023). "In contrast, using qRT-PCR and immunohistochemistry, DNMT1 and DNMT3B expressions were shown to be elevated in carcinomas compared to non-neoplastic tissue and further enhanced in higher-stage carcinomas." (PMID 37894317, 2023). "The positive pan-cancer correlations with m1A RNA methylation regulatory proteins YTHDF2 and ALKBH1, m5C methylation regulatory proteins DNMT1, DNMT3B, and ALYREF, and m6C RNA methylation regulatory proteins HNRNPC, HNRNPA2B1, and ELAVL1 were particularly significant." (PMID 36090896, 2022). "SIRT1 may facilitate cancer progression by epigenetically modulating the polycomb repressor complex 4 (PRC4) comprising DNMT1, DNMT3b, polycomb group (PcG) proteins, embryonic ectoderm development isoform 2 (EED2), and enhancer of zeste homolog 2 (EZH2)." (PMID 35054489, 2022). "MSI2 (RNA‐binding protein Musashi homolog 2) is known to be an important regulator in cancer initiation, progression, and drug resistance, whereas DNMT3B (DNA Methyltransferase 3 Beta) mediates DNA methylation, and play a crucial role in in hematopoietic stem cells." (PMID 34862757, 2022). "We further observed that cancer-free smokers had significantly lower miR-29b expression and non-significant but slightly higher DNMT3B mRNA expression than cancer-free non-smokers did." (PMID 35627221, 2022). "Unexpectedly, the expression of LEPROT was positively correlated with that of DNMT1 and DNMT3A but not DNMT3B in most cancers and was consistently positive-correlated with DNMT2 in all cancers." (PMID 34804118, 2021). "Collectively, the DNMT3A, DNMT3B, DNMT1, and ALYREF might function as poor prognosis predictors in cancer progression." (PMID 34325709, 2021). "As the HOXB7 methylation, which has already been described in several cancers and has been shown to relate with patient’s prognosis, the search for genes that are hypermethylated in response to HOXB7-binding to DNMT3B is also an important and interesting approach to pursue." (PMID 34063128, 2021). "However, in cancer cells, DNMT3A and DNMT3B enzymes synergistically enhance the DNMT1 activity and shift its activity towards de novo DNA methylation." (PMID 33498667, 2021). "Indeed, TERT synergized with Sp1 to stimulate the DNMT3B promoter activity, and moreover, Sp1 inhibition significantly attenuated TERT-mediated DNMT3B up-regulation, while its over-expression restored DNMT3B expression in TERT-depleted cancer cells." (PMID 31284662, 2019). "Notably, the reversal of Warburg effect was achieved by employing a dietary-phytochemical, which inhibits the DNMT3B, resulting in the reduced DNA-methylation at exon-10 and hence, PKM-splicing switch from cancer-specific PKM2 to normal PKM1." (PMID 31675998, 2019). "Functional studies also revealed that miR-148b-3p could act as a tumor suppressor via directly targeting distinct oncogenes such as DNMT3b, CCK2R, DNMT1, CEA and AMPKα1 in these cancers." (PMID 29661252, 2018). "The levels of DNMT3B and DNMT3A are often increased in various cancer tissues and cell lines." (PMID 30405408, 2018). "Using human cancer cell lines as a model system, we show that metformin functions to alter DNA methylation in a genome-wide fashion and that this action is at least in part mediated by the H19/SAHH/DNMT3B axis." (PMID 27775072, 2017).